CD4 (CD4 molecule)
Diseases named in the same sentence as CD4 in open-access papers (continued):
Sharing a sentence is not in itself a finding about the gene and the disease.
CMV retinitis (42 papers, 2011 to 2025). "Statistical analysis showed a significant association (p < 0.05) between low CD4 counts and the prevalence of CMV retinitis, highlighting the vulnerability of patients with severe immunosuppression." (PMID 39006338, 2024). "The most critical predictor for CMV retinitis is a CD4+ count below 50 cells/μL, with other risk factors including male gender, high HIV viral load, low CD8+ T-cell counts, and lack of HAART therapy." (PMID 39599491, 2024). "It is associated with the presence of inactive CMV retinitis, combination antiretroviral therapy with protease inhibitors, and evidence of at least partial immune reconstitution suggested by increased CD4+ cell counts." (PMID 35573011, 2022). "Cytomegalovirus retinitis was the most common ocular opportunistic infection and was most often associated with CD4+ T-cell count < 50 cells/μL." (PMID 33824735, 2021). "We have also shown that persons having a CMV-DNA level of more than 2000 copies/mL and persons with CD4 cell count <50/μl have a higher risk of developing CMV retinitis." (PMID 32318357, 2020). "Cytomegalovirus retinitis is a treatable cause of blindness in people with human immunodeficiency virus (HIV) typically with CD4 counts <50 cells/mm3." (PMID 31723570, 2019). "It is well established that, at extremely low absolute CD4 count (<50 CD4 T-cells/mm3) HIV-infected individuals are at risk of opportunistic CMV infections such as CMV retinitis." (PMID 29232408, 2017). "Baseline CD4 cell count is, however, generally considered a critical parameter in assessing risk for CMV retinitis." (PMID 25336901, 2014). "The investigators note that a CD4 count lower than 50 cells/mm3 was the single most important risk factor for the development of CMV retinitis, with a hazard ratio of 136 (95% confidence interval, 30–605) and an incidence rate of 3.89/100 person-years." (PMID 25336901, 2014). "Taken together, the number of CD4+ T lymphocyte in peripheral blood is an empirical indicator on occurrence, progress, alleviation and regression of CMV retinitis in clinical diagnostic and management." (PMID 22115120, 2011). "In addition, CD4 + cell count <50 cells/μL was found to be another risk factor for CMV retinitis (AOR 1.7, 95% CI 1.01–2.78)." (PMID 32318357, 2020). "A CD4 + T lymphocytes count below 100 cells/μL is associated with retinal or conjunctival microvasculopathy, Cytomegolovirus (CMV) retinitis, Varicella – Zoster Virus retinitis, cryptococcosis, microsporidiosis, HIV encephalopathy and progressive multifocal leuco-encephalopathy." (PMID 27487853, 2016). "Lower CD4 count (per 100 /μL decrement, OR 3.9, 95% CI 1.85–8.30, p<0.001) was also significantly associated with CMV retinitis, whereas presence of CMV diseases other than retinitis showed a trend toward association that was not statistically significant (OR 3.9, 95% CI 0.78–19.1, p = 0.097)." (PMID 26375282, 2015). "The median time from transplantation to diagnosis with CD4+ counts < 200 cells/μL was 126 days (range, 45–562 days), comparable to the median time from transplantation to diagnosis of CMV retinitis (151 days)." (PMID 41179870, 2025). "Two key factors in CMV retinitis development are CD4+ T lymphocyte count and CMV viral load in the aqueous humor." (PMID 39599491, 2024). "Compared with HIV-related CMV retinitis, phenotyping of lymphocytes revealed less frequently reduced CD4 + and CD8 + counts." (PMID 39107686, 2024). "Studies have shown that the prevalence of CMV retinitis in HIV-infected patients can be as high as 20-30% in those with CD4 counts below 50 cells/mm3 though with effective ART, the prevalence has decreased to around 2% in some cohorts." (PMID 39006338, 2024). "CMV retinitis has also been seen in patients with normal CD4 counts on corticosteroids or immunosuppressants like azathioprine for other diseases." (PMID 39599491, 2024).
CMV retinitis (continued). "CMV retinitis is likely to develop in AIDS patients when the number of CD4+ T-cells in the peripheral blood decreases below 50 cells/μL." (PMID 39066272, 2024). "CMV retinitis was diagnosed based on positive serologic testing and a low cluster of differentiation 4 (CD4) count, with concurrent SARS-CoV-2 infection detected." (PMID 39599491, 2024). "CMV retinitis in persons living with HIV is usually observed when CD4 + cells are below 50 cells/mm3." (PMID 39107686, 2024). "We additionally assessed immune markers during CMV retinitis (leukocyte, lymphocyte, CD4 + cell and CD8 + cell counts as well as immunoglobulin levels)." (PMID 39107686, 2024). "Despite the widespread use of ART, CMV retinitis remains prevalent, particularly in patients with low CD4+ T cell (CD4) counts." (PMID 39006338, 2024). "CMV retinitis in persons living with HIV (PLWH) is usually observed when CD4 + cells are below 50 cells/mm3 and represents one of the most frequent opportunistic infections defining AIDS." (PMID 39107686, 2024). "Other studies have suggested that the prevalence of CMV retinitis remains unchanged within groups with different CD4+ T-cell counts." (PMID 38133300, 2023). "Although the CD4+ T-cell count remains a pivotal marker in assessing immune status, its direct correlation with specific ocular manifestations, such as CMV retinitis and RD, remains inconclusive, underscoring the nuanced nature of HIV-related ocular diseases." (PMID 38133300, 2023). "HIV patients are recommended to have a thorough fundus examination before HAART initiation and a close follow-up especially in those with low CD4 counts to avoid the progression of CMV retinitis." (PMID 35573011, 2022). "The four cases with CMV retinitis had CD4+ T-cell counts below 50 cells/μL, with a mean value of 36.4 ± 5.2 cells/μL." (PMID 33824735, 2021). "Occurence of CMV retinitis in patients of NHL with high CD4 counts can be due to exhaustion and senescence of T cells which are major dysfunctional states in the tumor microenvironment." (PMID 34611773, 2021). "Clinical patterns of CMV Retinitis, CD4 counts at the time of presentation and the duration of treatment along with recurrences and time for recurrence of retinitis were assessed." (PMID 34611773, 2021). "In our study, the mean CD4+ count in persons with CMV retinits was significantly lower than that in non-CMV retinitis patients." (PMID 32318357, 2020). "In patients with HIV infections, the CD4+ T lymphocyte count, and peripheral blood quantitative CMV-DNA levels were found to be independent risk factors for CMV retinitis (P < 0.05)." (PMID 32318357, 2020). "We have demonstrated that the CD4+ T lymphocyte count, and peripheral blood quantitative CMV-DNA levels in patients with HIV infection are independent risk factors for CMV retinitis." (PMID 32318357, 2020). "Cytomegalovirus retinitis screening based on CD4 count is essential to early recognition because visual acuity and symptoms are unreliable." (PMID 31723570, 2019). "Cytomegalovirus retinitis was responsible for only 1 (5.9%) case and it occurred in a participant with a CD4 count of 136 cells/mm3 and the highest viral load count of 1,474,676 copies/mL." (PMID 28127467, 2016). "CMV retinitis recorded the highest viral load of 1,474,676 copies/mL and mean CD4 count of 136 cells/mm3." (PMID 28127467, 2016). "CMV retinitis is reported to occur in patients with extreme immune suppression, usually with CD4 count of <50 cells/mm3." (PMID 28127467, 2016). "Spontaneous resolution of CMV retinitis has been reported in patients with increased CD4 count relating to antiretroviral therapy." (PMID 28127467, 2016). "Of the 24 patients with CMV retinitis, 14 patients had CD4 count <50 /μL, whereas 6 patients had CD4 50–99 /μL and 4 patients had CD4 100–199 /μL." (PMID 26375282, 2015).
CMV retinitis (continued). "The prevalence of any ocular diseases and CMV retinitis were 22% and 3% in patients with CD4 <200 /μL, respectively, but were only 5.4% and 0% in patients with CD4 count ≥200 /μL." (PMID 26375282, 2015). "The result showed that the prevalence of ocular diseases among HIV-1-infected patients with CD4 ≥200 /μL was 5.4% (CMV retinitis 0%), far lower than 22% (CMV retinitis 3%) among patients with CD4 <200 /μL." (PMID 26375282, 2015). "CMV retinitis is a complication of late-stage human immunodeficiency virus (HIV) infection and is associated with CD4+ T cell counts less than 50/μL." (PMID 25089078, 2014). "Our data support the findings of other studies: that in patients taking HAART, CMV retinitis is increasingly rare, and when it does occur, it is usually in patients with a CD4 cell count lower than 50 cells/mm3." (PMID 25336901, 2014). "The mean CD4-count of patients with posterior segment lesions like CMV retinitis (93.8 cells/mm3), retinal detachment (74.7 cells/mm3), tuberculous chorioretinitis (96 cells/mm3), and ARN (64 cells/mm3) was less than 100 cells/mm3." (PMID 27355047, 2014). "The one case with CMV retinitis (representing 2% of all patients screened) had a CD4 count of 6 cells/mm3 (CD4% =3) at the time of screening." (PMID 25336901, 2014). "CMV retinitis that occurred in 47 patients in the group, who had CD4 count <50/mL, maintained CMV as an opportunistic agent of the immunocompromised ones." (PMID 25408732, 2014). "Ganciclovir p.o. was administered until CD4 increased by 50 copies/μL above the level at which the presence of CMV retinitis was detected in asymptomatic patients and by 70 copies/μL in symptomatic patients." (PMID 25408732, 2014). "Our review in 2007–2008 of the cohort of 24 patients seen found only one patient with CMV retinitis; this patient had a CD4 count of 6 cells/mm3." (PMID 25336901, 2014). "CMV retinitis, retinal detachment, tubercular chorioretinitis, and acute retinal necrosis were all seen in patients with CD4-count less than 100 cells/mm3." (PMID 27355047, 2014). "Jacobson et al10 reported five cases in whom the CD4 counts were higher than 195 cells/mm3 at the time of diagnosis of CMV retinitis." (PMID 25336901, 2014). "About 35% of individuals infected with HIV in low-income countries have a CD4+ T lymphocyte count less than 100 cells/μL before starting ART treatment; these are patients at risk for CMV retinitis." (PMID 25552774, 2014). "CMV retinitis screening is recommended at 3-month intervals in patients with a CD4+ T-lymphocyte count inferior to 50 cells/μL because 15% of patients with active CMV retinitis are asymptomatic." (PMID 23691386, 2013). "The low CD4+ T cell count at the initiation of HAART and the large area of cytomegalovirus retinitis were associated with an increased incidence of IRU." (PMID 23800125, 2013). "The CMV retinitis occurred in 3 out of 56 patients with CD4+ T lymphocyte counts at level of 99 to 50 cells/μl (prevalence 5.4%, 95% confidence interval: 1.1, 14.9)." (PMID 22115120, 2011). "In this study, CD4+ T lymphocyte counts in 4 patients with CMV retinitis were > 50 cells/μl (157 cells/μl, 53 cells/μl, 99 cells/μl, 97 cells/μl separately)." (PMID 22115120, 2011). "No CMV retinitis was observed in 65 patients with CD4+ T lymphocyte counts between 350 to 200 cells/μl and one CMV retinitis out of 69 patients with CD4+ T lymphocyte counts between 199 to 100 cells/μl (prevalence 1.4%, 95% confidence interval: 0.0,7.8)." (PMID 22115120, 2011). "Therefore, in patients undergoing such immunosuppressive therapies, a declining CD4+ T-cell count can serve as an early warning signal for CMV retinitis, indicating the urgent need for preemptive ocular screening and initiation of appropriate treatment." (PMID 41179870, 2025). "CMV retinitis remains a critical concern, especially in those with low CD4 counts." (PMID 39006338, 2024). "CMV retinitis was found in cases with a CD4 level of <200/mL." (PMID 37763724, 2023).
CMV retinitis (continued). "However, the CD4+ T-cell count of patients with CMV retinitis and RD in our study was above 500 cells/μL." (PMID 38133300, 2023). "Patients with IRU might suffer from CMV retinitis or systemic CMV infection at a very low level of CD4 counts before HAART initiation." (PMID 35573011, 2022). "Moreover, 30% of PLHIVs with CD4+ T lymphocyte counts below 50 cells/μL have CMV retinitis with blindness mainly due to posterior retinal detachment in these persons." (PMID 32318357, 2020). "The median CD4 count of 24 cases with CMV retinitis was 27 /μL (IQR 15–71 /μL, range 7–158 /μL)." (PMID 26375282, 2015). "The results of the present study showed the presence of ocular diseases and CMV retinitis in 26% and 5% of patients with CD4 <50 /μL, and in 22% and 3% of patients with CD4 <200 /μL, respectively, but only in 5.4% and 0% of patients with patients with CD4 count ≥200 /μL." (PMID 26375282, 2015). "It is well-known that CMV retinitis typically occurs in patients with CD4 count <50 /μL." (PMID 26375282, 2015). "However, CMV retinitis can also occur in patients with CD4 >50 /μL, as in the present study the CD4 count was 50–199 /μL in 10 (42%) out of 24 CMV retinitis cases." (PMID 26375282, 2015). "Six cases had HIV retinopathy without sight loss; one case had sight-threatening CMV retinitis associated with a CD4 count of 6 cells/mm3." (PMID 25336901, 2014). "It should be noted, however, that CMV retinitis may occur in patients with CD4 counts higher than 50 cells/mm3, and that our screening criteria would therefore miss these individuals." (PMID 25336901, 2014). "In 1992, Pertel et al6 reported that based on Kaplan–Meier survival curves, the percentage of patients developing CMV retinitis by 27 months with baseline CD4 lymphocyte counts of 0–50, 51–100, and 101–250 cells/mm3 was 41.9%, 26.3%, and 14.7%, respectively (log-rank test, P=0.003)." (PMID 25336901, 2014). "This may be because retinal detachment was seen as complication of CMV retinitis and tuberculous retinochoroiditis which generally occur in low CD4-count." (PMID 27355047, 2014). "CMV retinitis were diagnosed in patients with CD4 under 50/μL (one case with 199/μL)." (PMID 25408764, 2014). "The occurrence of CMV retinitis was reversely correlated with the level of CD4+ T lymphocytes." (PMID 22115120, 2011). "Moreover, the CMV retinitis was diagnosed in 19 out of 113 patients with CD4+ T lymphocyte counts < 50 cells/μl (prevalence 16.8%, 95% confidence interval: 10.4, 25.0)." (PMID 22115120, 2011). "The obvious way to improve clinical management of CMV retinitis is to screen all patients with CD4 counts < 100 cells/μL with indirect ophthalmoscopy at the time they first present for care, and to provide systemic treatment with oral valganciclovir when active CMV retinitis is detected." (PMID 22115187, 2011). "CMV retinitis in NHL patients is usually of an indolent or granular type and can occur even in the presence of high CD4 counts as compared to patients with HIV." (PMID 34611773, 2021). "In that study, they only recruited patients with HIV infection who had CD4 < 100/μl and there were 16/100 patients with HIV infection diagnosed with CMV retinitis." (PMID 32318357, 2020). "Multivariate logistic regression analysis was performed with the confirmed CMV retinitis as the dependent variable and the age, sex, CMV-DNA, CD4+ cell counts as independent variables." (PMID 32318357, 2020). "In our series, two patients with CMV retinitis and RRD were HIV-infected and had low CD4+ leukocyte counts." (PMID 29164419, 2017). "For example, previous studies, among HAART-treated individuals with CMV retinitis, showed that memory CMV-specific CD4 and CD8 T-cells expanded several years after HAART initiation." (PMID 23786370, 2013). "CMV retinitis occurs only in profoundly immunocompromised HIV-infected patients, with CD4+ T-lymphocyte counts of less than 100 cells/mm3, but usually less than 50 cells/mm3." (PMID 23691386, 2013).
CMV retinitis (continued). "Whereas CMV retinitis is rarely seen in PLWH with CD4 + counts over 50 cell/mm3 and virtually never in patients with CD4 + counts over 100 cell/mm3, we found that only four patients (33.3%) had CD4 + counts under 100 cell/mm3." (PMID 39107686, 2024). "We performed laboratory diagnosis of CMV retinitis, which was confirmed with positive results of serologic testing for CMV (IgM and IgG) along with CD4 count of 16 cells/μL, CD8 count of 521 cells/μL, and a ratio of CD4/CD8 lymphocytes of 0.03." (PMID 39599491, 2024). "We found one series reporting CD4 + counts under 100 cell/mm3 in non-HIV-related CMV retinitis in 48% of their patients without details on the lymphocyte counts or immunoglobulin levels." (PMID 39107686, 2024). "Whereas the role of CD4 + and CD8 + T lymphocytes in the control of CMV infection has been largely demonstrated, the impact of the use of immunosuppressive drugs impairing humoral immunity on the incidence of CMV retinitis has been less reported." (PMID 39107686, 2024). "In contrast to HIV-related CMV retinitis, which is strongly associated with the level of CD 4 count, in non-HIV patients with CMV retinitis, CD4 count is an unreliable prognostic factor." (PMID 36192634, 2023). "All of our patients had a presenting CD4 count above 100 cells/mm3 and none of them were below 50 cells/mm3 (the level at which CMV retinitis usually occurs in HIV patients)." (PMID 34611773, 2021). "There was, however, a statistically significant difference in CD4+ T-lymphocyte count between CMV retinitis and non-CMV retinits patients (P = 0.0002)." (PMID 32318357, 2020). "Cytomegalovirus retinitis was the most frequently encountered complication of HIV infection in this cohort, occurring in 34.6 % of patients with CD4+ T cell counts <50 cells/μL and in 63.4 % of patients with CD4+ T cell counts <200 cells/μL." (PMID 26809342, 2016). "Participants without CMV retinitis were invited for repeated examinations every 3 months until their CD4 count exceeded 100 cells/μL." (PMID 27788232, 2016). "In our study, CMV retinitis in 4 patients with CD4+ T lymphocyte counts > 50 cells/μl were diagnosed without ART." (PMID 22115120, 2011). "Moreover, no universally accepted threshold for CD4+ or CD8+ T-cell counts predictive of CMV retinitis has been established." (PMID 41179870, 2025). "CMV retinitis was diagnosed in 24 (1.6%) of the 1,515 study patients, 14 (5%) of 308 patients with CD4 <50 /μL, 20 (4%) of 490 with CD4 <100 /μL, 24 (3%) of 731 with CD4 <200 /μL, and none among patients with CD4 count ≥200 /μL." (PMID 26375282, 2015). "Notably, the introduction of anti-HIV therapy (i.e., ART) has increased CD4+ T-cell counts and reduced the proportion of the population with CD4+ T-cell counts below 50 cells/μL, thus reducing the incidence of CMV retinitis; however, it has not yet been eradicated." (PMID 39066272, 2024).